TRAV5 (T cell receptor alpha variable 5)
Description:
V region of the variable domain of T cell receptor (TR) alpha chain that participates in the antigen recognition. Alpha-beta T cell receptors are antigen specific receptors which are essential to the immune response and are present on the cell surface of T lymphocytes. Recognize peptide-major histocompatibility (MH) (pMH) complexes that are displayed by antigen presenting cells (APC), a prerequisite for efficient T cell adaptive immunity against pathogens. Binding of alpha-beta TR to pMH complex initiates TR-CD3 clustering on the cell surface and intracellular activation of LCK that phosphorylates the ITAM motifs of CD3G, CD3D, CD3E and CD247 enabling the recruitment of ZAP70. In turn ZAP70 phosphorylates LAT, which recruits numerous signaling molecules to form the LAT signalosome. The LAT signalosome propagates signal branching to three major signaling pathways, the calcium, the mitogen-activated protein kinase (MAPK) kinase and the nuclear factor NF-kappa-B (NF-kB) pathways, leading to the mobilization of transcription factors that are critical for gene expression and essential for T cell growth and differentiation. The T cell repertoire is generated in the thymus, by V-(D)-J rearrangement. This repertoire is then shaped by intrathymic selection events to generate a peripheral T cell pool of self-MH restricted, non-autoaggressive T cells. Post-thymic interaction of alpha-beta TR with the pMH complexes shapes TR structural and functional avidity.
Synonyms: TCRAV15S1; TCRAV5S1
Gene: T-cell receptor variable (V) gene on chromosome 14 (21,749,178 to 21,749,705, forward strand). Ensembl gene ENSG00000211779.
Subcellular location: Cell membrane
Gene Ontology:
Biological process: response to bacterium
Cellular component: plasma membrane
Homologues: Orthologues: macaque TRAV5 (92% identical), mouse Trav3-4 (68% identical), mouse Trav3-1 (64% identical), mouse Trav3d-3 (64% identical), mouse Trav3n-3 (64% identical), rat AABR07017733.1 (64% identical), mouse Trav3-3 (63% identical). Paralogues in human: TRAV13-2 (58% identical), TRAV13-1 (57% identical), TRAV39 (42% identical), TRAV21 (40% identical), TRAV36DV7 (38% identical), TRAV10 (37% identical), TRAV17 (37% identical), TRAV20 (37% identical), TRAV24 (35% identical), TRAV38-2DV8 (35% identical), TRAV6 (35% identical), TRAV38-1 (35% identical), and 11 more.
Diseases named in the same sentence as TRAV5 in open-access papers:
TRAV5 is named in the same sentence as 2 diseases in open-access papers, as found by Europe PMC text mining. Sharing a sentence is not in itself a finding about the gene and the disease. The quoted sentences say what the papers report.
autoimmune disease (1 paper, 2025). A disorder resulting from loss of function or tissue destruction of an organ or multiple organs, arising from humoral or cellular immune responses of the individual to their own tissue constituents. "We also identified biased usage of certain TCR V and J gene segments, such as TRAV12.3, TRAV5, TRBV23.1 and TRBV3.1, which have been implicated in other autoimmune diseases." (PMID 40583051, 2025).
TRAV5 also shares sentences with these, for which no sentence is quoted: tumor (1 paper).